PINK1 (PTEN induced kinase 1)
Diseases named in the same sentence as PINK1 in open-access papers (continued):
Sharing a sentence is not in itself a finding about the gene and the disease.
Parkinson disease (continued). "Mutations in phosphatase and tensin homolog (PTEN)-induced putative kinase 1 (PINK1), which is encoded by the PARK6 gene, were identified in cases with early-onset Parkinson’s disease." (PMID 26569220, 2015). "Recent cell-based and in vivo studies have revealed that PINK1 acts upstream of another gene product that is relevant to Parkinson's disease, Parkin." (PMID 25609704, 2015). "Increased TOR activity has been observed in case of Fragile X syndrome, Huntington's, PINK1 based Parkinson's disease models." (PMID 25361581, 2014). "The present study aimed to investigate the association between T313M polymorphism at exon 4 of the PTEN-induced putative kinase 1 (PINK1) gene and Parkinson’s disease (PD) in the Uygur and Han populations of Xinjiang, China." (PMID 24944636, 2014). "Mutations in various proteins such as LRRK2, PARK2), phosphatase and tensin homolog (PTEN)-induced putative kinase 1 (PINK1), and (DJ-1) have been observed in familiar cases of Parkinson, which only account for 10–15% of diagnosed cases." (PMID 25136294, 2014). "Mutations in Parkinson's disease associated genes like those encoding Parkin, PINK1 (PTEN-induced putative kinase 1), HTRA2 (high temperature requirement protein A2), and DJ-1 affect mitochondrial morphology and function and cause oxidative stress." (PMID 24288463, 2013). "The asymmetry of radioligand uptake for Parkinson's disease with GBA or LRRK2 mutations was greater than that for Parkinson's disease with alpha synuclein, PINK1 or Parkin mutations." (PMID 23935950, 2013). "The involvement of Parkin and PINK1 in mitochondrial dysfunction, oxidative injury, and impaired functioning of the ubiquitin-proteasome system has been investigated in light of Parkinson's disease pathogenesis." (PMID 23533695, 2013). "It has been shown that early onset Parkinson's disease is associated with certain genetic mutations such as Parkin, LRRK2, and PINK1." (PMID 24455416, 2013). "Olfactory dysfunctions are a common feature in PINK1 Parkinsonism and consist typically of defective odor identification and discrimination both in human and in animal PD models." (PMID 24009736, 2013). "The involvement of PINK1 and Parkin in the mitochondrial dysfunction has now been intensively investigated in Parkinson's disease pathogenesis." (PMID 23533695, 2013). "We also highlight recent advances in our understanding of Fbxo7 function in Parkinson's disease, where it functions in the regulation of mitophagy with PINK1 and Parkin." (PMID 24107298, 2013). "Genes including ATP13A2, DJ-1, GIGYF2, HTRA2, LRRK2, PARK2 (parkin), PINK1, SNCA and UCHL1 were associated with either autosomal dominant or recessive form of Parkinson's disease." (PMID 24688734, 2013). "Scans were available from 37 cases of monogenetic Parkinson's disease (7 glucocerebrosidase (GBA) mutations, 8 alpha-synuclein, 3 LRRK2, 7 PINK1, 12 Parkin)." (PMID 23935950, 2013). "In patients with Parkinson’s disease (PD), FRs have been associated with several genes, such as SNCA, parkin, DJ-1, PINK1 and LRRK2, with a defect in complex I of the mitochondrial electron-transport chain and oxidative stress in substantia nigra." (PMID 23344052, 2013). "Loss-of-function mutations in PINK1 and/or PARK2 genes have been linked with the early onset of hereditary forms of Parkinson’s disease." (PMID 23267366, 2012). "Recently, TRAP1 was reported as a downstream phosphorylation target of PTEN-induced kinase 1 (PINK1), a gene involved in the onset of Parkinson’s disease, in rat and human cell lines." (PMID 23284813, 2012). "Independent studies identified α-synuclein, Pink1, Parkin, DJ-1, and Leucine-rich repeat kinase 2 (LRRK2) as commonly mutated genes in Parkinsonism." (PMID 22792111, 2012).
Parkinson disease (continued). "Genetic linkage studies of Parkinson's Disease (PD) have identified susceptibility loci in five genes which include SNCA (PARK1), Parkin (PARK2), PTEN-induced putative kinase (PINK1;PARK6), DJ-1 (PARK7) and Leucine rich repeat kinase 2 (LRRK2; PARK8)." (PMID 21812969, 2011). "Loss-of-function mutations or DA neuron-specific inactivation of the respective Drosophila homologues of PINK1, Parkin, DJ-1, LRRK2, and HtrA2 can also lead to parkinsonism-like DA cell loss and locomotor defects." (PMID 20522007, 2010). "(Aβ= amyloid beta; APP= amyloid precursor protein; DJ1= Parkinson’s disease (autosomal recessive, early onset) 1; PINK1= phosphatase and tensin induced putative kinase 1; SOD1= superoxide dismutase 1)." (PMID 20938400, 2010). "DJ-1 gene, PTEN-induced putative kinase 1 (PINK1) gene and parkin (PRKN) gene mutations are responsible for autosomal recessive Parkinson cases." (PMID 19399218, 2009). "We also made an unexpected observation that NCS-1 interacts with several mitochondrial proteins, including Pink1, a gene that contributes to familial Parkinson's disease." (PMID 19320994, 2009). "The aim of this study was to further elucidate the function of PINK1 in the prevention of DAergic degeneration seen in Parkinson's disease." (PMID 18560593, 2008). "Valid animal models of PINK1 parkinsonism should recapitulate the motor symptoms seen in patients as well as the underlying nigrostriatal deficiencies and neuropathological findings." (PMID 18560593, 2008). "Here, we follow up on those results, screening not only LRRK2, but also PRKN, SNCA and PINK1 in a cohort of early-onset and late-onset familial Portuguese Parkinson disease patients." (PMID 18211709, 2008). "Synonymous and non-synonymous substitutions found in the parkin and PINK1 gene in affected with parkinsonism." (PMID 19087301, 2008). "To date, associations between three different genes/loci and early-onset Parkinson's disease (EOPD) have been identified: PARK2, which encodes parkin, PARK6, which encodes PINK1, and PARK7, which encodes DJ-1." (PMID 17324265, 2007). "Recently, mutations in the PINK1 (PARK6) gene were shown to rarely cause autosomal-recessively transmitted, early-onset parkinsonism." (PMID 16354302, 2005). "Monogenic typical Parkinsonism: The initial presentation – including early-onset Parkinsonism and a favorable response to levodopa – resembles that seen in EOPD patients with mutations in PARK2, PINK1, or DJ-1." (PMID 41517720, 2026). "Thus, genetic predispositions, such as variations in the PINK1 and GST genes, seem to amplify the effects of pesticide exposure, resulting in earlier onset and progression of Parkinson disease." (PMID 40243837, 2025). "These technologies, including whole-exome sequencing (WES) and whole-genome sequencing (WGS), have facilitated the identification of pathogenic mutations in genes such as APP, PSEN1, and PSEN2 in Alzheimer’s disease (AD), as well as LRRK2, SNCA, and PINK1 in Parkinson’s disease (PD)." (PMID 40076852, 2025). "Approximately 5–10% of patients, however, develop a “monogenic form of Parkinson’s Disease”, which is caused by pathogenic variants in SNCA, LRRK2, and VPS35, genes exhibiting autosomal dominant inheritance, along with PRKN, PINK1, and DJ-1, genes which follow autosomal recessive inheritance." (PMID 40564955, 2025). "Additionally, some familial forms of Parkinson's disease have been linked to loss-of-function mutations in PINK1 or PRKN in humans, and genetic knockout of Pink1 or Prkn expression in mice results in central nervous system defects (49, –51)." (PMID 39928869, 2025). "Understanding the mechanisms by which Parkin and PINK1 interact with the STING pathway opens new avenues for therapeutic interventions in Parkinson’s disease and potentially other neurodegenerative disorders characterized by mitochondrial dysfunction and inflammation." (PMID 39969761, 2025).
Parkinson disease (continued). "Astrocytes are known to be become reactive in Parkinson’s disease that includes neuroinflammation, and several genes implicated in Parkinson’s are expressed in both astrocytes and neurons (e.g., PARK7, SNCA, PLA2G6, ATP13A2, LRRK2, PINK1, and PARK2)." (PMID 40972575, 2025). "While advances have been made in understanding the role of PINK1 in mitochondrial dynamics and the development of Parkinson’s disease, the current tools available to study PINK1 only provide snapshots of PINK1 activity and cannot distinguish PINK1 activity at the single cell level." (PMID 41279391, 2025). "The PINK1 SNP IVS1-7 A→G was mostly found in patients with early-onset Parkinson disease." (PMID 40243837, 2025). "In other work, dermal fibroblasts from a patient carrying the homozygous mutation p.W437X in PINK1, which results in partial loss‐of‐function of the gene to manifest as early‐onset parkinsonism, did not reveal mtCN variation." (PMID 40474850, 2025). "Monogenic defects in mitophagy, such as PINK1 or Parkin deficiency, are associated with early‐onset parkinsonism, and there is a significant phenotypic overlap with our EPG5‐mutated patients with parkinsonism." (PMID 41053928, 2025). "Also in Parkinson's disease, the interaction between PINK1 and Beclin1 leads to increased mitochondrial contact in the ER, which in turn promotes the formation of autophagosomes." (PMID 40406921, 2025). "Nucleotide analogs such as kinetin triphosphate (KTP) were reported to enhance PINK1 activity and may represent a therapeutic strategy for the treatment of Parkinson’s disease." (PMID 38241364, 2024). "Variants in seven genes (LRRK2, GBA1, PRKN, SNCA, PINK1, PARK7 and VPS35) have been formally adjudicated as causal contributors to Parkinson’s disease; however, individuals with Parkinson’s disease are often unaware of their genetic status since clinical testing is infrequently offered." (PMID 39074992, 2024). "Some studies have shown that ceramides play a crucial role in Pink1 related Parkinson’s disease." (PMID 38803440, 2024). "In addition to a direct role in aggregate dissolution, BAG2 functions as a neuroprotective upstream regulator of the PINK1/PARKIN signaling pathway in an in vitro Parkinson’s disease model." (PMID 38928492, 2024). "Additionally, the human PINK1 gene (PTEN-induced kinase 1, Park6), a significant gene in Parkinson's disease, accumulates in the outer mitochondrial membrane and serves as a crucial marker of mitochondrial damage." (PMID 39179991, 2024). "PINK1 (PTEN induced kinase 1) and PRKN (parkin RBR E3 ubiquitin protein ligase) are the key players of this Ub-tagging process and complete loss of either enzyme leads to early-onset Parkinson disease (PD)." (PMID 38802071, 2024). "Furthermore, whole-exome sequencing did not identify pathogenic (or likely pathogenic) variants in the PINK1, SYNJ1, and PODXL genes and other known genes associated with early-onset parkinsonism." (PMID 39332416, 2024). "PTEN-induced putative kinase 1 (PINK1) is an outer mitochondrial membrane (OMM) kinase, whereas Parkin is an E3 ubiquitin ligase present in the cytosol, both of which are gene products mutated in Parkinson’s disease." (PMID 39183973, 2024). "There is a genetic component to the disease, which accounts for between 10 and 15% of cases, with several individual genes (such as LRRK2, SNCA, PINK1, PARK7 and PRKN) associated with Parkinson’s disease and over 90 gene loci that can increase the risk of developing Parkinson’s disease." (PMID 38276234, 2024). "Among the strongest reference bursts, the most highly cited articles in recent years were “Parkinson’s disease,” “Parkin and PINK1 mitigate STING-induced inflammation,” and “Mitochondrial dysfunction in Parkinson’s disease: New mechanistic insights and therapeutic perspectives”." (PMID 39350973, 2024).
Parkinson disease (continued). "PTEN-induced kinase 1 (PINK1), a protein kinase, plays a significant role in mitochondrial quality control and cellular stress response, and its mutated forms lead to early-onset Parkinson's disease." (PMID 38508312, 2024). "Parkinson’s disease (PD) is associated with mutations in several proteins that have been linked with proteasomes, including alpha-synuclein (α-SNCA), protein deglycase DJ-1 (PARK7), UCHL1, PTEN-induced kinase 1 (PINK1), and PD protein 2 (PARK2, parkin)." (PMID 38067336, 2023). "Mechanistic crosstalk between PINK1 and mortalin requires further study, as PINK1-mortalin interaction could be a potential target for new therapeutic approaches in certain diseases, including Parkinson’s disease and malignant tumors." (PMID 36819105, 2023). "TRAP-1 is also crucial in some other pathologies such as Parkinson disease, as a mutation in PTEN-induced Putative Kinase (PINK1), which phosphorylates and activates TRAP-1, is present in the disease, where PINK1-mutated cells cannot activate TRAP-1 and apoptosis occurs." (PMID 37345199, 2023). "Specifically, PINK1 regulates complex I function and prevents the accumulation of reactive oxygen species (ROS), which has been directly related to neurodegenerative diseases such as Parkinson’s disease." (PMID 37299685, 2023). "In fact, several studies have revealed that melatonin enhances mitophagy by the PINK1-parkin pathway or autophagy-related genes in brain ischemia, acute brain injury, or Parkinson’s disease models all of which are quite different from glucocorticoid-induced neurodegeneration." (PMID 36810730, 2023). "PINK1 (PTEN Induced Kinase 1), known as a mitochondrial protein-coding gene, has been involved in neurodegeneration and associated with nervous system disorders like parkinsonism, mitochondrial dysfunction, and stroke." (PMID 38034591, 2023). "The major progress of the research on PINK1 was to better understand Parkinson disease." (PMID 37940999, 2023). "Importantly, this study discloses a wayof pharmacologically blocking PARL to boost PINK1/Parkin-dependentmitophagy, whose enhancement is explored as a therapeutic approachfor the treatment of Parkinson’s disease." (PMID 36540942, 2023). "Loss of the mitophagy genes pink-1 and pdr-1/parkin results in heightened susceptibility to neurodegeneration caused by 6-hydroxy- dopamine (6-OHDA), a chemical model of dopaminergic and noradrenergic neurodegeneration in Parkinson’s disease." (PMID 37681856, 2023). "The core components of the mitophagy machinery are linked to genetic forms of neurodegeneration: the Parkinson’s disease genes PTEN-induced kinase 1 (PINK1; PARK6) and the cytosolic E3 ubiquitin ligase Parkin (PARK2) are centrally placed in the mitophagy pathway." (PMID 34389813, 2022). "Likewise, SNCA (α-synuclein), PARK2 (parkin), PARK7 (DJ-1), PINK1 and LRRK2 are the mutated genes of parkinsonism, among which mutations in both PARK2 (parkin) and LRRK2 are the most common genetic causes." (PMID 36478742, 2022). "Among its pleiotropic effects, Vitamin D exerts a neuroprotective effect in a mouse model of Parkinson’s, inducing autophagy; moreover, it suppresses mitochondrial complex I and activates PINK1/PARKIN-dependent mitophagy to limit oxidative stress, while promoting damaged mitochondria clearance." (PMID 35625553, 2022). "Thus, inhibition of USP30 represents an actionable target to correct pathologies associated with PINK1 or PRKN defects, such as Parkinson disease or pulmonary fibrosis." (PMID 34844982, 2022). "Ambra1 acts as an alternative mediator in PINK1/Parkin-mutant Parkinson's disease patients." (PMID 34225732, 2021). "For example, Pink1−/− rats exhibit vocalization deficits beginning with reduced loudness at 2 months of age, an aspect of this model that has great translational relevance due to the nearly ubiquitous reduction in vocal loudness in human Parkinson disease." (PMID 33928251, 2021).
Parkinson disease (continued). "Therefore, the role of Pink1/Parkin in the mitochondrial quality control has been investigated intensively in neurodegenerative diseases, including Parkinson’s and Alzheimer’s." (PMID 34940029, 2021). "Interestingly, this includes mutant PINK1 and Parkin Drosophila models of genetic Parkinson’s disease." (PMID 34152608, 2021). "The presence of a missense variant in PINK1 in a Parkinson’s disease case does not automatically imply pathogenicity." (PMID 34893635, 2021). "Similarly, in Parkinson’s disease, mitophagy upregulation by Mitochondria receptor Nip3-like protein X (Nix) restores mitochondrial function to protect against PINK1/Parkin related Parkinson’s disease." (PMID 34440658, 2021). "PINK1 and PARK2 (Parkin) are mutated in inherited forms of early onset Parkinson’s disease." (PMID 35118415, 2021). "We focused on the mitochondria as their dysfunction is widely associated with Parkinson’s disease, and the Pink1- genetic model has a disrupted mitophagy pathway due to the absence of a functional PINK1 protein." (PMID 34074800, 2021). "Early onset LRRK2-related PD as well as milder forms of DNAJC6-related Parkinsonism may present with a phenotype resembling pure PRKN/PINK1 recessive cases." (PMID 34630269, 2021). "Additionally, in a cellular model of Parkinson’s disease, a neo-substrate of the PINK1 enzyme has been identified." (PMID 34768767, 2021). "The Pink1−/− rat is a useful model to study Parkinson disease." (PMID 33928251, 2021). "Interestingly, mutations in the PTEN-induced kinase-1 (PINK-1), a ubiquitin kinase participating in mitochondrial quality control, cause recessive early onset Parkinson's disease." (PMID 34215308, 2021). "Hence, it remains to be established what role the PINK1/PARKIN-induced mitophagy plays in the emergence of the Parkinson pathology in human patients." (PMID 34944035, 2021). "Indeed, mitochondrial localization is essential for PINK1 and Parkin to exert their genuine functions, inhibition of which promotes Parkinson's disease." (PMID 34676411, 2021). "Dysregulation of the PINK1/Parkin-mediated mitophagy is essential to Parkinson’s disease." (PMID 34148057, 2021). "Although mutations or deletions of Parkin or PINK1 cause Parkinson disease in humans, mice deficient in either PINK1 or Parkin do not display any related phenotype." (PMID 32274386, 2020). "PINK1/PARKIN: The most well studied pathway of mitophagy involves the mitochondrial serine/threonine PTEN-induced kinase 1 (PINK1) and the cytosolic E3-ligase PARKIN, two proteins found to be mutated in familial forms of early onset Parkinson’s disease." (PMID 33352783, 2020). "The ionophore valinomycin, on the other hand, is a respiratory chain uncoupler that activates mitophagy via the PINK1/Parkin signaling pathway and plays an important role in clearing dysfunctional mitochondria through mitophagy in people with Parkinson’s disease." (PMID 33339339, 2020). "Mutations in PINK1 and Parkin/PRKN cause the degeneration of dopaminergic neurons in familial forms of Parkinson’s disease but the precise pathogenic mechanisms are unknown." (PMID 32060339, 2020). "Except for use in chemotherapy, KR and its ProTides activate the Parkinson’s Disease Associated PTEN-Induced Putative Kinase 1 (PINK1) independent of mitochondrial depolarization." (PMID 32955614, 2020). "Indeed, in hiPSC-based Parkinson's disease models, PINK1 nitrosylation—also observed in transgenic Parkinson's mice models—correlates with reduced Parkin recruitment efficiency and mitophagy disruption." (PMID 33224433, 2020). "Two Parkinson’s disease factors, PINK1 and Parkin, are considered key mediators of damage-induced mitophagy, and promoting mitochondrial fission is sufficient to suppress the pathological phenotypes in Drosophila Pink1/parkin mutants." (PMID 33085661, 2020). "However, most of the current researches of Pink1 and Parkin were based on some common neurodegenerative diseases, such as Parkinson disease." (PMID 30290401, 2019).